P4HB (prolyl 4-hydroxylase subunit beta)
Diseases named in the same sentence as P4HB in open-access papers (continued):
Sharing a sentence is not in itself a finding about the gene and the disease.
bladder cancer (12 papers, 2020 to 2024). "Based on the differential expression of apoptosis-related genes, we established a risk model to predict the prognosis of bladder cancer patients, in which P4HB promotes BLCA progression." (PMID 37845668, 2023). "P4HB has been reported to be associated with a variety of cancer and oncological outcomes, like bladder cancer from our previous study." (PMID 37480146, 2023). "While P4HB has been recently identified as a novel prognostic biomarker associated with overall survival of bladder cancer patients, TMEM74 has been shown to promote tumor cell survival by inducing autophagy." (PMID 33925460, 2021). "These preliminary in vitro experimental results confirmed that P4HB may be associated with the development and progression of bladder cancer." (PMID 32903592, 2020). "But there are many studies on the role of P4HB in other diseases, such as bladder carcinoma, oesophageal cancer and kidney renal clear cell carcinoma." (PMID 37270661, 2023). "Elevated expression of P4HB has been reported in several solid tumors, such as ovarian cancer, bladder cancer, and prostate cancer." (PMID 36226178, 2022). "P4hb can increase the occurrence of reactive oxygen species, bladder cancer, prostate cancer, brain, CNS, and other related cancers." (PMID 36080339, 2022). "While higher expression of APOL1, ATG4B, ITGA3, WDR45, CASP3, and PRKCD is associated with favorable survival in human bladder cancer patients, increased ULK2 and P4HB mRNA levels are negatively correlated to overall survival of bladder cancer patients." (PMID 33925460, 2021). "When tested as individual gene, 9 genes from the 11-ARG signature (APOL1, ATG4B, CASP3, ITGA3, P4HB, PRKCD, ULK2, and WDR45) exhibited a significant association between mRNA expression levels and overall survival of bladder cancer patients." (PMID 33925460, 2021). "Since the expression level of P4HB was upregulated in bladder cancer tissues and cells, we further investigated the effect of silencing P4HB on the viability and invasion of BUC cells in vitro." (PMID 32903592, 2020). "The present study also further confirmed that P4HB promotes bladder cancer cell growth." (PMID 37845668, 2023). "Moreover, we demonstrated that knockdown of P4HB in human bladder cancer cells in vitro dramatically inhibited cancer cell invasion." (PMID 32903592, 2020). "The high expression of ABCB9, SPTBN2, GULP1, IGF1, P4HB, NES and DPYSL2 and the low expression of ANXA6, OAS1, RAD9a, DNASE2B and FANCF would be beneficial to the prognosis of bladder cancer patients." (PMID 37845668, 2023). "The si-P4HB and the corresponding negative control were transfected into bladder cancer cells and RT-qPCR confirmed that P4HB was successfully knocked down." (PMID 37845668, 2023). "It has been reported that OTUB1, P4HB, and EHMT2 could regulate the malignant phenotype of bladder cancer cells via the ERS related URP pathway." (PMID 35004850, 2021). "For example, P4HB retrieved from HADb website has been identified as a prognostic biomarker for BLCA, which could dramatically inhibit the invasion and proliferation of bladder cancer cells, providing novel insights for autophagy-mediated tumor progression." (PMID 35140317, 2022). "Finally, we validated that the mRNA and protein expression levels of P4HB were upregulated in four bladder cancer cell lines (T24, J82, EJ, and SW780) and found that knockdown of P4HB dramatically inhibited the invasion and proliferation of bladder cancer cells." (PMID 32903592, 2020).
glioblastoma (12 papers, 2017 to 2024). The most malignant astrocytic tumor (WHO grade IV). "The endoplasmic reticulum stress response pathways have been linked to increased sensitivity to chemotherapy in glioblastoma multiforme through the inhibition of P4HB." (PMID 38305808, 2024). "P4HB inhibition has been also linked to chemosensitivity in glioblastoma multiforme via the endoplasmic reticulum stress response pathways." (PMID 36499183, 2022). "The P4HB is a chaperone protein of ER stress signaling; it was reported that miR-210 was P4HB-targeting in temozolomide (TMZ)-resistance glioblastoma multiforme (GMB) cells." (PMID 33477489, 2021). "In line with this, miR-210 overexpression was shown to decrease P4HB, a chaperone protein related to the ER stress response, in glioblastoma multiforme cells study." (PMID 33477489, 2021). "Endoplasmic reticulum (ER) chaperone Prolyl 4-hydroxylase, beta polypeptide (P4HB) has previously been identified as a novel target for chemoresistance in glioblastoma multiforme (GBM)." (PMID 29069756, 2017). "BACH2 has known tumor immunosuppressive capacity, and P4HB upregulation may be involved with glioblastoma multiforme as noticed for integration sites recovered from the ART-treated individuals, thus suggesting that oncogenic genes may play a role in the overlap." (PMID 32970634, 2020).
colon carcinoma (11 papers, 2019 to 2024). "P4HB is highly expressed in colon cancer, and knockdown of P4HB promotes cancer cell apoptosis." (PMID 34944885, 2021). "In addition, recent reports have revealed that P4HB and RCN1 acted as tumor-suppressor factors in liver cancer, colon cancer, lung cancer and prostate cancer." (PMID 35436915, 2022).
prostate carcinoma (10 papers, 2013 to 2024). A carcinoma that arises from epithelial cells of the prostate gland. "Cg17054691 is located in the P4HB gene, aberrant methylation and differential expression of which is implicated in the aetiology of prostate cancer." (PMID 37528416, 2023). "This study aimed to evaluate the expression of P4HB and SOX4 in prostatic carcinoma and investigate their possible diagnostic or prognostic roles." (PMID 39118797, 2024). "The current study revealed that P4HB and SOX4 were significantly expressed in PAC compared to NPH which suggests their oncogenic role in prostatic carcinoma and strongly indicates its diagnostic capability which was further confirmed by ROC curve analysis." (PMID 39118797, 2024). "In conclusion, deregulation of the miR-18a-5p/P4HB network can contribute to the developmental origins of prostate cancer in maternally malnourished offspring, highlighting the need for improving maternal healthcare during critical windows of vulnerability early in life." (PMID 36499183, 2022). "This study aims to investigate P4HB and SOX4 expression in prostatic carcinoma, their possible roles, and clinical significance." (PMID 39118797, 2024).
hepatocellular carcinoma (8 papers, 2016 to 2023). A malignant tumor that arises from hepatocytes. "In hepatocellular carcinoma (HCC), P4HB was overexpressed in HCC tissues and cell lines and higher P4HB levels were associated with advanced disease and worse prognosis." (PMID 38029391, 2023). "In liver cancer, knockdown of P4HB inhibits the migration and invasion of HepG2/ADR cells, as demonstrated by culturing HepG2 cells (a human hepatocellular carcinoma cell line) in the presence of increasing concentrations of adriamycin." (PMID 34944885, 2021).
lung carcinoma (7 papers, 2021 to 2024). "Lung cancer-related changes, such as increased platelet levels of P4HB from the PDI family, underscore the importance of this antithrombotic drug target for the hypercoagulable state in certain cancer types." (PMID 34066760, 2021). "P4HB, a member of the collagen prolyl 4-hydroxylase enzyme, also showed significant increase in Hyp, likely due to increased prolyl 4-hydroxylase activity in lung cancer." (PMID 36026437, 2022). "Of these, Cathepsin B (CTSB), Protein disulfide–isomerase (P4HB) and Cystatin-B (CSTB) were found upregulated in myeloma, lung cancer or colorectal cancer." (PMID 38791048, 2024). "For pathophysiological explorations of platelet proteome changes in patients with lung cancer we concentrated on four candidates described to be involved in the processing of coagulation proteins, which are F13A1 and the ER proteins P4HB, CALR and HSPA5." (PMID 34066760, 2021). "Accordingly, lower levels of ITGA2B and increased levels of the ER proteins P4HB, CALR and HSPA5 in patients with lung cancer and LA suggest some common affected pathways in their prothrombotic pathology." (PMID 34066760, 2021). "Elevated levels of ER chaperones P4HB, CALR and HSPA5 indicated the induction of the ER unfolded protein response (UPR) in platelets of patients with lung cancer." (PMID 34066760, 2021). "In the current study, however, the plasma concentrations of P4HB were not increased in patients with lung cancer." (PMID 34066760, 2021). "In the actual study, P4HB concentration was not significantly increased in the plasma of patients with lung cancer." (PMID 34066760, 2021).
clear cell renal cell carcinoma (6 papers, 2021 to 2024). "As for kidney cancer, overexpression of P4HB is an unfavorable prognostic factor in patients with clear cell renal cell carcinoma." (PMID 34620162, 2021). "P4HB is also highly expressed in renal clear cell carcinoma and significantly related to poor OS." (PMID 34944885, 2021). "P4HB is an ATG, which is significantly increased in clear cell renal cell carcinoma (ccRCC) at the mRNA and protein level, showing a high ability of diagnosis and prognosis." (PMID 33960661, 2021).
liver cancer (6 papers, 2021 to 2024). An epithelial or non-epithelial malignant neoplasm that arises from the liver. "In addition, P4HB was also found to be associated with liver cancer chemoresistance." (PMID 38029391, 2023). "It has been reported that P4HB played an important role in modulating chemoresistance in liver cancer, BLCA, and malignant glioma." (PMID 37790935, 2023). "In addition, liver cancer cells with overexpressed P4HB favored cancer cell growth and epithelial–mesenchymal transition, and also enhanced cancer cell chemoresistance." (PMID 35436915, 2022).
diabetes (5 papers, 2018 to 2025). "Sod1 and P4hb showed significant differences in mRNA expression between the livers of gerbils with diabetes and control animals, implying that these genes play an important role in the mechanism of diabetes in gerbils." (PMID 29394254, 2018). "PDIA1/prolyl 4-hydroxylase subunit β (P4HB) is needed for efficient proinsulin maturation and β-cell health in diet-induced obesity animal models and PDIA1 expression is increased in human diabetes." (PMID 40244115, 2025).
ovarian carcinoma (5 papers, 2020 to 2023). A malignant neoplasm originating from the surface ovarian epithelium. "The analysis results revealed that P4HB expression was higher in bladder, brain, breast, kidney, lung, prostate, ovarian cancers, and lymphoma tumors than in normal tissues." (PMID 32903592, 2020). "In ovarian cancer, P4HB was also expressed higher in tumor tissues compared to adjacent tissues." (PMID 38029391, 2023). "Similarly, the sensitivity of ovarian cancer cells to cisplatin and phytochemicals might be regulated by the expression of P4HB." (PMID 38029391, 2023).
breast tumor (4 papers, 2009 to 2025). "Prolyl-4-hydrolase beta-isoform (P4HB) was found to be upregulated in HER-2/neu-positive breast tumours in contrast to our findings." (PMID 19367286, 2009).
COVID-19 (4 papers, 2021 to 2025). A disease caused by infection with severe acute respiratory syndrome coronavirus 2. "A previous study also found PDIs, particularly P4HB and PDIA6, in COVID-19 platelets." (PMID 37681923, 2023). "Finally, the levels of two different protein disulfide isomerases, P4HB and PDIA6, which support thrombosis, were increased in the platelets of COVID-19 patients." (PMID 34859078, 2021).
pancreatic cancer (4 papers, 2018 to 2024). "On the other hand, the upregulation of P4HB has been reported by a few studies at the proteomics level in pancreatic cancer and pancreatic islets of type I diabetes patients." (PMID 37945567, 2023). "Notably, among these genes, SOD2, P4HB, and TNFSF10 were identified as hub genes associated with adverse prognostic outcomes in pancreatic cancer." (PMID 38685045, 2024). "We established and validated a prognostic model for pancreatic cancer with 7 signatures, including ADH1C, APOE, RAP1GAP, NPC1L1, P4HB, SOD2, and TNFSF10." (PMID 38685045, 2024).
type 2 diabetes (4 papers, 2018 to 2023). "We also identified seven genes (Sardh, Slc39a7, Pfn1, Arg1, Cth, Sod1 and P4hb) in the liver and one gene (Fabp4) in the adipose tissue that may be associated with type 2 diabetes in gerbils." (PMID 29394254, 2018).
cervical cancer (3 papers, 2021 to 2025). A primary or metastatic malignant neoplasm involving the cervix. "The upregulated ligand receptor pairs in the cervical cancer group were SPP1 − CD44, FN1 − SDC4, FN1 − SDC1, FN1 − CD44, CD99 − CD99, and the downregulated ligand receptor pairs were PPIA – BSG, LGALS9 − P4HB, LGALS9 − CD44." (PMID 41384115, 2025).
esophageal squamous cell carcinoma (3 papers, 2021 to 2023). Esophageal squamous cell carcinoma (ESCC) is a type of esophageal carcinoma (EC) that can affect any part of the esophagus, but is usually located in the upper or middle third. "In addition, EVs produced by oesophageal squamous cell carcinoma (ESCC) were reported to induce apoptosis in muscle cells through releasing prolyl 4-hydroxylase subunit beta (P4HB), which activates the ubiquitin-dependent proteolytic pathway." (PMID 37998333, 2023). "Additionally, EVs secreted by esophageal squamous cell carcinoma (ESCC) cells induced apoptosis of muscle cells through release of prolyl 4-hydroxylase subunit beta (P4HB) that activates the ubiquitin-dependent proteolytic pathway." (PMID 35441960, 2022).
lung adenocarcinoma (3 papers, 2020 to 2022). A carcinoma that arises from the lung and is characterized by the presence of malignant glandular epithelial cells. "For example, high expression of P4HB as well as low expression of BTG2 and CIT was associated with poor overall survival of lung adenocarcinoma patients (p-value of log-rank test < 0.05)." (PMID 36138770, 2022). "MiRNA hsa-mir-30a and lncRNA AC104472.1 constituted regulatory module for lung adenocarcinoma a with TPI1, KPNA2, MET, HSP90B1, P4HB, DSP, CDH1, and ENO1." (PMID 36138770, 2022).
malignant glioma (3 papers, 2017 to 2023). A grade III or grade IV glioma arising from the central nervous system. "Our group has previously identified another ER chaperone protein, P4HB, to be associated with TMZ resistance in malignant glioma." (PMID 29069756, 2017). "Targeting P4HB could attenuate temozolomide resistance in malignant glioma by inhibiting ER stress response pathways." (PMID 34620162, 2021). "This study aimed at delineating the oncogenic role of P4HB in malignant glioma." (PMID 29069756, 2017). "In addition to clinical grading (p = 0.013), P4HB expression in malignant glioma was also found to be significantly correlated with angiogenesis as indicated by CD31 expression (p = 0.009), and a positive association with VEGF (p = 0.07)." (PMID 29069756, 2017).
non-small cell lung carcinoma (3 papers, 2017 to 2024). A group of at least three distinct histological types of lung cancer, including non-small cell squamous cell carcinoma, adenocarcinoma, and large cell carcinoma. "P4HB is overexpressed in non-small cell lung cancer (NSCLC), and decreased P4HB expression following drug treatment predicts better clinical outcome." (PMID 28052026, 2017).
Obesity (3 papers, 2019 to 2025). Accumulation of substantial excess body fat. "Furthermore, previous studies found that PDIA1 contributes to oxidative maturation of proinsulin in the endoplasmic reticulum to support insulin production and ß-cell health in diet-induced obesity, indicating that P4HB could indirectly influence insulin production and ß-cell health." (PMID 36226178, 2022).
osteogenesis imperfecta (3 papers, 2019 to 2024). Osteogenesis imperfecta (OI) comprises a heterogeneous group of genetic disorders characterized by increased bone fragility, low bone mass, and susceptibility to bone fractures with variable severity. "Moreover, P4HB missense mutations cause mild osteogenesis imperfecta, and also Cole–Carpenter syndrome." (PMID 38396997, 2024). "P4HB has been reported to be a novel candidate gene for a severe type of osteogenesis imperfecta." (PMID 39062769, 2024).
thrombosis (3 papers, 2016 to 2021). "In this study we also detected elevated P4HB levels in the plasma of LA patients with thrombosis history." (PMID 34066760, 2021). "Remarkably, in patients with lung cancer as well as in LA-positive patients with thrombosis history we identified a highly significant increase in the PDI family member, P4HB, in platelets, which also manifest this ER chaperone as a highly purposive antithrombotic drug target." (PMID 34066760, 2021).
bladder urothelial carcinoma (2 papers, 2021 to 2022). "P4HB has a significant prognostic potential in bladder urothelial carcinoma by serving as an autophagy-related gene." (PMID 35436915, 2022).
Hyperglycemia (2 papers, 2019 to 2022). An increased concentration of glucose in the blood. "Interestingly, antibody against PDIA1/P4Hb precedes the onset of hyperglycemia in murine NOD mice, as early as 4 weeks of age." (PMID 36389721, 2022).
kidney cancer (2 papers, 2020 to 2021). Primary or metastatic malignant neoplasm involving the kidney. "Because immunotherapy has always been a hot topic in kidney cancer research, and P4HB is related to antigen processing and presentation, we concluded that P4HB is likely to promote the development and progression of pRCC through immunomodulation." (PMID 34620162, 2021).
lupus nephritis (2 papers, 2022). Glomerulonephritis in the context of systemic lupus erythematosus. "In some SLE patients, antibodies against the HU1 bacterial peptide recognized P4HB as an autoantigen on the membrane of renal cells, inducing lupus nephritis." (PMID 35632621, 2022).
lymphoma (2 papers, 2017 to 2022). A malignant (clonal) proliferation of B- lymphocytes or T- lymphocytes which involves the lymph nodes, bone marrow and/or extranodal sites. "Consistent with this notion, PDI (P4HB) is overexpressed in a variety of cancer types including brain, lymphoma, kidney, prostate, lung and ovarian cancers." (PMID 29262583, 2017).
osteoporosis (2 papers, 2020 to 2023). A condition of reduced bone mass, with decreased cortical thickness and a decrease in the number and size of the trabeculae of cancellous bone (but normal chemical composition), resulting in increased fracture incidence. "In addition, target interaction network analysis by network-based visual analysis (miRNet) showed that five genes (GAPDH, PLOD1, LMNA, WDR1, and P4HB) with five miRNAs (hsa-let-7a/b-5p, hsa-let-7b-5p, hsa-mir-16-5p, hsa-mir-18a-5p, and hsa-mir-192-5p) were associated with osteoporosis by DisGeNET." (PMID 38132172, 2023). "The significance of environmental factors in diseases has been shown by a subcellular proteomics study that identified four candidate osteoporosis-related molecules, namely P4HB (β subunit of prolyl 4-hydroxylase), CD36, β1 integrin, and actinin-1." (PMID 32927783, 2020).
prostate tumor (2 papers, 2022 to 2023). "According to our research, P4HB is a new oncogene connected to the development of prostate tumors." (PMID 37480146, 2023).
Stroke (2 papers, 2014 to 2018). Sudden impairment of blood flow to a part of the brain due to occlusion or rupture of an artery to the brain. "We found that P4hb-expressing fibroblasts displayed a preferential accumulation in the scar region of post-stroke aged brains, and may have contributed to the formation of the fibrotic scar via TGF-beta signaling." (PMID 24672479, 2014).
and neck cancers (1 paper, 2020). "However, expression of P4HB in esophageal, head, and neck cancers and leukemia was lower than expression in other cancers in some data sets." (PMID 32903592, 2020).
Autoimmunity (1 paper, 2022). The occurrence of an immune reaction against the organism's own cells or tissues. "Conversely, the involvement of P4HB in autoimmunity was shown to result from cross-reactivity with microbial antigens." (PMID 35632621, 2022).